CASP8 (caspase 8)
Diseases named in the same sentence as CASP8 in open-access papers (continued):
Sharing a sentence is not in itself a finding about the gene and the disease.
ischemic stroke (10 papers, 2015 to 2025). A stroke disorder caused by obstruction of blood flow to the brain, due to thrombotic (local blood clot formation) or embolic (due to a blood clot or other material traveling from another site) event. "Elevated levels of FADD (Fas-associated protein with death domain) and caspase-8 were associated with an increased incidence of ischemic stroke." (PMID 37305740, 2023). "An association between plasma levels of caspase-8 and incidence of ischemic stroke as well as coronary events has been found, indicating that such proteins can be used as biomarkers for injury." (PMID 35310100, 2022). "Other events, such as ischemic stroke and coronary events, are also known to be associated with higher levels of caspase-8." (PMID 35310100, 2022). "The emerging role of IL-18 in CNS pathologies, as ischaemic stroke and inflammation-driven neurodegeneration has been supported by multiple studies and Casp8 was reported in association with neuron-specific apoptotic processes and as a major pathogenetic factor in Alzheimer’s disease." (PMID 38105266, 2023). "The temporal and spatial activation of caspase-8 was further investigated in a permanent middle cerebral artery occlusion mouse model of ischemic stroke." (PMID 27566702, 2016). "Analysis of brain tissue samples from a pMCAO mouse model of ischemic stroke, at 6, 24 and 48 h post artery occlusion, illustrated a temporal and spatial activation for caspase-8 in Iba1-positive myeloid cells." (PMID 27566702, 2016). "Here, we present in vivo evidence for the activation of caspase-8 and caspase-3 in microglia/macrophages in post-mortem tissue from human ischemic stroke subjects." (PMID 27566702, 2016). "Therefore, the decrease of neuronal apoptosis mediated by the inactivation of the caspase-8/-9/-3 pathway is an important way for ST-T in the motor function improvement in ischemic stroke." (PMID 34804173, 2021). "Whereas inhibition of caspase-8 and/or caspase-3 could be used as therapeutic strategy to combat the inflammatory response initiated upon ischemic stroke remains controversial." (PMID 27566702, 2016). "Collectively, these data illustrate the temporal and spatial activation of caspase-8 and -3 in microglia/macrophages occurring upon ischemic stroke and suggest that the expression of these caspases could be used in neuropathological diagnostic work." (PMID 27566702, 2016). "A study treating ischemic stroke with a monoclonal antibody targeting TNF- α found that the antibody favorably modulates microglial M1 / M2 polarization, rebalances Th 17 / Treg, cell dynamics, and suppresses Caspase-8-mediated GSDMD cleavage to prevent microglial pyroptosis." (PMID 40786625, 2025). "However, an increase in caspase-8 expression without any association with caspase-3 involves the Fas-associated protein with death domain (FADD) and is associated with an increased incidence of ischemic stroke." (PMID 37885997, 2023).
malaria (10 papers, 2012 to 2024). Malaria is a serious and sometimes fatal disease caused by a parasite that commonly infects a certain type of mosquito which feeds on humans. "Indeed, it was later observed that, in experimental malaria, CASP8 expression was associated with apoptosis of infected cells, as well as with the death of T cells and other immune cells in the spleen." (PMID 37794476, 2023). "Consistent with these discoveries, we observed a marked increase in the renal expression of CASP3, CASP8 and particularly TRIAL mRNAs in the kidney tissue of mice with malaria-associated AKI." (PMID 38787228, 2024). "Considering individuals with P. falciparum-malaria, the DEL/DEL genotype of the rs3834129 (CASP8) was associated with lower rates of parasite density (P = 0.009; OR = 0.383; 95% CI 0.113–1.295)." (PMID 37794476, 2023). "In malaria models in mice, caspase-8 controls the expression of pro-IL-1β and TNF-α as well as their release in plasma." (PMID 33805003, 2021). "Together, these results indicate that while redundant in these malaria models, the role of caspase-8 is complementary but distinct from the canonical inflammasome that involves caspases-1 and GSDM-D activation." (PMID 32929083, 2020). "Here, the authors show that caspase-8 is a central mediator of systemic inflammation in rodent malaria and that monocytes from malaria patients express active caspases-1, -4 and -8." (PMID 32929083, 2020). "Here, we report that caspase-11 and the homologous inflammatory human caspase-4, as well as caspase-8, are highly activated during Plasmodium infection, both in mouse and malaria patients." (PMID 32929083, 2020). "In conclusion, our results demonstrate that caspase-1, caspase-8, the mouse caspase-11, and its human ortholog caspase-4 are all activated in monocytes from P. vivax and P. falciparum malaria patients and mouse malaria models." (PMID 32929083, 2020). "Located in the promoter region of the CASP8 gene, the INS/INS genotype significantly increases the susceptibility to malaria caused by P. falciparum, while the DEL/DEL genotype reduces the chances for mono-infection by P. falciparum and for infection by multiple species." (PMID 37794476, 2023). "The contribution of caspase-8 in cytokine induction was shown even in the pathogenesis of malaria." (PMID 33805003, 2021). "process caspase-8, indicating their potential role in IL-1β release and pathogenesis of malaria." (PMID 32929083, 2020). "As caspase-8 controls the release/expression of two key cytokines on Plasmodium-induced disease, it should be considered a potential target for therapeutic intervention in malaria patients." (PMID 32929083, 2020). "Similarly, parasite-activated mesangial cells may likely express TRAIL, CASP3 and CASP8 to resolve glomerular hypercellularity by triggering apoptosis and consequently ameliorating malaria-induced glomerulonephritis in ECM." (PMID 38787228, 2024). "Hence, our results indicate that the deleterious role of caspase-8 in the hypersensitivity to septic shock in this malaria model may also involve the induction of TNFα expression." (PMID 32929083, 2020). "The work of Gazzinelli’s group used genetic and molecular approaches to demonstrate that CASP-8, CASP-1, mouse CASP-11, and its human ortholog CASP-4 were upregulated in monocytes from malaria patients and mice malaria models." (PMID 33672278, 2021). "While redundant, our data indicate that in these malaria models the mechanism by which caspases-1/11 promotes IL-1β release involves GSDM-D, whereas caspase-8 seems to mediate expression of pro-IL-1β and TNFα." (PMID 32929083, 2020). "Knockout of caspase-8/1/11 or caspase-8/GSDMD resulted in disruption of TNF-α and IL-1β production, uncovering a supplementary and indispensable role for caspase-8 and GSDMD in malaria pathogenesis." (PMID 35795683, 2022).
malaria (continued). "In the present study, the apoptosis occurring in malaria infected placenta did not involve death receptor pathway as no change in the expression of Fas gene and activation of caspase 8 was observed compared with non-infected placenta." (PMID 22396790, 2012).
Cerebral ischemia (9 papers, 2004 to 2024). Restriction of arterial blood supply to the brain associated with insufficient oxygenation to support the metabolic requirements of the tissue. "Additionally, after cerebral ischemia, Fas-associated death domain protein binding to procaspase-8 triggers activation of caspase 8; subsequently, caspase-3 is activated and causes caspase 3-dependent cell death." (PMID 34257822, 2021). "Of note, cerebral ischemia triggers both intrinsic pathway that originates from mitochondrial crash associated stimulation of caspase-9 and the extrinsic pathway that derives from death receptors activation and subsequent stimulation of caspase-8." (PMID 28428752, 2017). "Recently, very early treatment with zonisamide was shown to decrease morbidity by suppressing the expression of caspase-3, caspase-8, and calpain-1, inhibiting the apoptosis of neuronal cells after cerebral ischemia." (PMID 36824441, 2022). "In line with our data, others have observed activation of both caspase-9 and caspase-8 following hypoxic stress in animal models of brain ischemia." (PMID 15613236, 2004). "Similar experiments were carried out to evaluate whether CASP3 or CASP6 activation was dependent on CASP8: at 2 days after cerebral ischemia or 14 days after retinal ischemia, there was a significant reduction in the levels of CASP3 and CASP6 cleavage products in Z-IETD-FMK-treated rats (P<0.001)." (PMID 26539914, 2015). "We decided to study CASP8 in our model due to its contribution to neuronal pathologies like TBI, brain ischemia, and seizures." (PMID 38389906, 2024). "Mechanistically, we showed that CASP6 or CASP8 inhibition (Z-VEID-FMK or Z-IETD-FMK) reduced the levels of cleaved procaspase-3 and procaspase-6 following cerebral ischemia." (PMID 26539914, 2015).
endometrial cancer (9 papers, 2006 to 2024). Primary or metastatic malignant neoplasm involving the endometrium (mucous membrane that lines the endometrial cavity). "Recently, progesterone (20 μM) was shown to trigger apoptosis via the activation of caspase-8 in ovarian and endometrial cancer cells." (PMID 34066763, 2021). "Lower CNA numbers have been detected in CASP8-mutated oral squamous cell carcinoma and in CTNNB1-mutated endometrial cancer." (PMID 27831464, 2016). "We have recently demonstrated that histone deacetylase inhibitor, Vorinostat, applied as a single therapy or in combination with caspase-8 downregulation exhibits high anti-tumoral activity on endometrial carcinoma cell lines." (PMID 24651472, 2014). "Here we demonstrate that the HDAC inhibitor LBH589 can increase TRAIL-mediated caspase-8 activation and subsequent extrinsic cell death in endometrial cancer cells." (PMID 21687633, 2011). "The downregulation of MMP23B (Matrix Metalloproteinase 23B) reduced the cell viability of endometrial cancer cells, upregulated the expression levels of CASP3 (Caspase-3), CASP8 (Caspase-8) and CASP9 (Caspase-9) in cells, and inhibited cell migration and invasion." (PMID 38782818, 2024). "Nevertheless, we think that the fact of combination Vorinostat with Caspase-8 inhibition displays tumoricidal activity regardless of oxidative stress status enhances its value as possible treatment for endometrial cancer." (PMID 24651472, 2014).
Obesity (9 papers, 2019 to 2025). Accumulation of substantial excess body fat. "In a wider population, we show that the expression of LUBAC components in AT is significantly associated with improved metabolic fitness in patients with obesity potentially by preventing caspase-8–dependent cell death." (PMID 40961178, 2025). "Both apoptosis and pyroptosis appeared to be highly enriched in GSEA data of HoipA-KO mice, yet caspase-8 deletion was sufficient to prevent lipodystrophy and obesity-associated metabolic syndromes such as IR and MASLD." (PMID 40961178, 2025). "Together, these data indicate that RIPK3 contributes to obesity-induced metabolic dysfunction, and this is likely, in part, through activation of caspase-8 signaling in myeloid cells." (PMID 39532538, 2025). "RIP3 is thought to maintain adipose tissue homeostasis and dampen inflammation by inhibiting caspase-8-dependent apoptosis of adipocytes, associated with a prevention of glucose intolerance, in the choline deficient-HFD dietary model of obesity." (PMID 38161978, 2023). "Twelve weeks of HIIT (running, 85%–90% maximum aerobic speed, 5 sessions/week) effectively reduced pro-apoptotic proteins, including cytochrome c release, caspase-8, and caspase-3 to suppress cardiomyopathy and HF in rats (3 weeks old) with obesity." (PMID 37608837, 2023). "As RIPK3 can regulate the death- and inflammation-inducing activity of both caspase-8 and MLKL in disease-causing macrophages, direct comparisons of mutant animals in the same obesity and MAFLD model are required to define their pathological roles and divergent activities." (PMID 39532538, 2025). "We therefore examined whether RIPK3 and caspase-8 contribute to pathological inflammatory changes in HFD-induced obesity." (PMID 39532538, 2025). "Additionally, obesity triggers cardiomyocytes to undergo apoptosis by enhancing mitochondrial permeability, cytochrome c release, caspase-8 and caspase-3 upregulation in cardiomyocytes." (PMID 37608837, 2023). "Here, we show that caspase-8 deletion is sufficient to prevent metabolic dysfunction caused by HOIP deficiency, positioning LUBAC as a key regulator of cell death in adipocytes and in the consequent onset of lipodystrophy and obesity-related metabolic dysfunction." (PMID 40961178, 2025). "Here, we directly contrast the contribution of RIPK3, along with caspase-8 in myeloid cells, and MLKL signaling in obesity and MAFLD development." (PMID 39532538, 2025). "Mechanistically, we show that the metabolic disorders, i.e., lipodystrophy and obesity-induced metabolic syndrome, in mice lacking HOIP in adipocytes is driven by caspase-8–mediated cell death." (PMID 40961178, 2025). "Our study reveals that caspase-8 induces damaging inflammation to saturated fatty acids, whereas MLKL uniquely regulates obesity and MAFLD via noncanonical actions on lipid metabolism." (PMID 39532538, 2025).
psoriasis (9 papers, 2017 to 2025). An autoimmune condition characterized by red, well-delineated plaques with silvery scales that are usually on the extensor surfaces and scalp. "In addition, we have previously demonstrated that inflammatory human skin diseases such as atopic dermatitis and psoriasis likewise exhibit a loss of epidermal caspase-8." (PMID 36112666, 2022). "In addition, the chronic down-regulation of caspase-8 underlies inflammatory skin diseases such as atopic dermatitis and psoriasis." (PMID 36112666, 2022). "To probe a possible link between caspase-8 down-regulation and methyltransferase expression, we utilized the imiquimod-induced model of psoriasis in mice." (PMID 36112666, 2022). "Previously, we have established the importance of the down-regulation of caspase-8 RNA in both physiological (wound healing) as well as pathological (atopic dermatitis and psoriasis) scenarios." (PMID 36112666, 2022). "For instance, MEG3/miR-21 axis contribute in the pathophysiology of psoriasis through modulation of caspase-8, cleaved caspase-8, cytc, and apaf-1." (PMID 32695942, 2020). "We found that the interaction of CASP10 - CASP1, CASP10- CASP3, CASP10- CASP4, CASP10- CASP9, CASP10- CASP12, CASP8 - CASP3, CASP8 - CASP4, and CASP1 - CASP12 is important for the risk of psoriasis." (PMID 30906769, 2019). "MEG3/miR-21 axis may regulate the expression of caspase-8, and further influence the proliferation and apoptosis of psoriasis keratinocyte, Act-HaCaT and Act- HHEK." (PMID 31660855, 2019). "Meanwhile, we confirmed that miR-21 influence the proliferation and apoptosis of cell by modulating caspase-8, and this finding may provide a new insight for the treatment of psoriasis." (PMID 31660855, 2019). "Psoriatic patients showed an increase in TNF-α expression, which could promote the activation of the death receptor-mediated pathway as verified by a significant increase of the expression of caspase-8 revealed for granulocytes in both forms of psoriasis." (PMID 30301214, 2018). "Several atypical NF-kB pathways were enriched and activated in psoriasis, such as NF-kB activation through FADD RIP-1 Pathway mediated by caspase 8 and10, TNFR2 and Dectin1 mediated noncanonical NF-kB pathway." (PMID 37861483, 2023).
renal carcinoma (9 papers, 2014 to 2023). A carcinoma arising from the epithelium of the renal parenchyma or the renal pelvis. "CASP8 has also been found to be overexpressed in a range of cancers including prostate and renal cancer where it is associated with a poor outcome." (PMID 35357426, 2022). "Ectopic expression of Par-4 in renal cancer cells sensitizes TRAIL-resistant Caki cells to apoptosis associated with activation of caspase-8, caspase-3 and modulation of DR5, Bcl-2, Akt, and NF-κB." (PMID 24523904, 2014). "We next tested whether the levels of CASP8 in renal cancer were associated with more aggressive disease by analyzing the mRNA levels of CASP8 in renal cancer tissues." (PMID 33828176, 2021). "Conversely, Caspase-8 expression is increased in colorectal, cervical and renal cancers compared to normal tissues." (PMID 37444381, 2023). "Taken together, these data demonstrate that high levels of CASP8 may serve as a biomarker for unfavorable outcome in patients with renal cancer." (PMID 33828176, 2021). "Patients with renal cancer recurrence exhibited higher levels of CASP8 mRNA when compared to patients who did not recur, and increased expression levels of CASP8 were associated with worse disease-free survival in renal cancer patients (p = 0.0071)." (PMID 33828176, 2021). "Likewise, high expression of CASP8 correlated with renal cancer-specific mortality (p = 0.01) and worse overall survival (p = 0.017)." (PMID 33828176, 2021).
Splenomegaly (9 papers, 2014 to 2024). Abnormal increased size of the spleen. "Loss of caspase-8 in myeloid cells led to splenomegaly in both young and aged mice." (PMID 26471282, 2015). "Casp8C362A/C362ARipk3−/− mice also develop splenomegaly, indicating the potential of catalytic activity of caspase-8 in immune homeostasis." (PMID 35064213, 2022). "Caspase-8 heterozygosity significantly delayed epidermal hyperplasia, but other aspects of the cpdm phenotype (e.g. splenomegaly and liver inflammation) remained." (PMID 25443632, 2014). "However, 10/10 mice which had received Casp8−/− BM cells developed a certain degree of anemia, 8/10 exhibited reduced platelet numbers and 4/10 displayed splenomegaly with increased WBC counts." (PMID 38637559, 2024). "In addition, Casp8ΔE385/ΔE385Ripk3−/− and Casp8ΔE385/ΔE385Mlkl−/− mice developed lymphopenia with severe splenomegaly instead of the lymphoproliferative disease as observed in Casp8−/−Ripk3−/− and Casp8−/−Mlkl−/− mice." (PMID 35064213, 2022). "Conversely, reduction in caspase-8 markedly ameliorated the skin phenotype but did not prevent splenomegaly or liver inflammation." (PMID 25443632, 2014).
squamous cell carcinoma (9 papers, 2014 to 2022). A carcinoma arising from squamous epithelial cells. "In squamous cell carcinoma, the inhibitor of DNA binding 3 (Id3) induced apoptosis through an Elk-1-caspase-8-dependent pathway." (PMID 30267330, 2018). "Upregulation of caspase-8 and the whole TNF-receptor signaling was seen in squamous carcinoma giving thus no direct evidence for pathway activity." (PMID 25568670, 2014).